MUCL3 (mucin like 3)
Description:
May modulate NF-kappaB signaling and play a role in cell growth.
Synonyms: C6orf37; DPCR1; PBLT; bCX105N19.6
Safety:
Unwanted effects reported when the protein is acted on. In parentheses: how it was acted on, where the effect was seen, and who reports it.
thrombocytopenia (source: ClinPGx)
Gene: Protein-coding gene on chromosome 6 (30,940,973 to 30,954,221, forward strand). Ensembl gene ENSG00000168631.
Subcellular location: Cell membrane; Cytoplasm
Genetic constraint (gnomAD): Loss-of-function variants: 43 observed, 74.78 expected, observed/expected ratio (o/e) 0.58, 90% interval 0.45 to 0.74. The synonymous counts are far from expectation, so gnomAD's model fits this gene poorly and the ratio says little. Missense variants: 1,429 observed, 1,697 expected, observed/expected ratio (o/e) 0.84, 90% interval 0.81 to 0.88. Synonymous variants: 522 observed, 653.99 expected, observed/expected ratio (o/e) 0.8, 90% interval 0.74 to 0.86.
Homologues: Orthologues: chimpanzee MUCL3 (93% identical), rat Mucl3 (16% identical), mouse Mucl3 (16% identical), macaque MUCL3 (15% identical).
Diseases named in the same sentence as MUCL3 in open-access papers:
MUCL3 is named in the same sentence as 8 diseases in open-access papers, as found by Europe PMC text mining. Sharing a sentence is not in itself a finding about the gene and the disease. The quoted sentences say what the papers report.
colorectal cancer (1 paper, 2024). A primary or metastatic malignant neoplasm that affects the colon or rectum. "In clinical practice, MUCL3 is considered a prognostic marker for immunogenic cell death associated with patients with colorectal cancer." (PMID 39518882, 2024).
Obesity (1 paper, 2022). Accumulation of substantial excess body fat. "We only found five genes shared between both groups (MUCL3, PGC, TCN1, TFF2, BPIFB1) that were upregulated in MO-low-IR but downregulated in MO-high-IR when compared with women without obesity." (PMID 35625760, 2022).
cancer (4 papers, 2018 to 2024). A tumor composed of atypical neoplastic, often pleomorphic cells that invade other tissues. "Specifically, MUCL3 has been confirmed to be associated with cancers and neuropsychiatric disorders." (PMID 39518882, 2024). "Volcano plot showed significantly upregulated transcripts of transmembrane 4 L6 family member 1 (TM4SF1), neuritin 1 (NRN1), MT2, mucin‐like protein 3 (MUCL3), complement component 4B (C4B) and insulin‐like growth factor‐binding protein 4 (IGFBP4) genes in treated KPC mice cancer cells." (PMID 38131168, 2023).
MUCL3 also shares sentences with these, for which no sentence is quoted: tumor (3 papers); pituitary adenomas (2); esophageal squamous cell carcinoma (1); gastric cancer (1); leprosy (1).